CREB1 (cAMP responsive element binding protein 1)
Diseases named in the same sentence as CREB1 in open-access papers (continued):
Sharing a sentence is not in itself a finding about the gene and the disease.
colorectal cancer (50 papers, 2010 to 2025). A primary or metastatic malignant neoplasm that affects the colon or rectum. "CREB1 enhances the malignant behavior of liver cancer cells, colorectal cancer cells and epithelial ovarian cancer." (PMID 39735673, 2025). "For example, circEZH2/IGF2BP2 enhances the stability of CREB1 mRNA to promote the progression of colorectal cancer." (PMID 40612865, 2025). "In colorectal cancer, CREB1 activates the transcription of CCAT1 (colon cancer associated transcript 1), which upregulates MYC, a potent oncogene." (PMID 39883338, 2024). "Recently, CREB1 was found to contribute to colorectal cancer cell plasticity through increasing transcription of the oncogenic lncRNA CCAT1 and upregulation of the NF‐κB pathways." (PMID 37929660, 2024). "For instance, in colorectal cancer, CREB1 activates MYC through lncRNA CCAT1, primarily promoting cell proliferation without affecting the regulation of integrin proteins and their associated suppression of metastasis." (PMID 39883338, 2024). "CircEZH2/miR-133b/insulin like growth factor 2 mRNA binding protein 2 (IGF2BP2) aggravates colorectal cancer progression via enhancing the stability of m6A-modified CREB1 mRNA." (PMID 38023219, 2023). "CREB1 plays an oncogenic role in various cancers, including bladder, lung, breast, and colorectal cancers." (PMID 34499007, 2021). "There are no previous data on CREB1 in CD, but it has been related to other diseases like human colorectal cancer, where CREB1 acts as a TF for tumor driver RRM2, or glioblastoma, where CREB1 acts as a mediator of the induction of TGFβ2." (PMID 29748492, 2018). "In this study, we found that the cAMP responsive element binding protein 1 (CREB1) acted as a transcription factor of RRM2 gene in human colorectal cancer (CRC)." (PMID 27801665, 2016). "In a similar manner, miR-205 has been shown to downregulate the CAMP responsive element binding protein 1 (CREB1), leading to growth suppression in colorectal cancer cells, as well as cell proliferation control through an interaction with PTEN, a growth repressor, in nasopharyngeal cancer." (PMID 34831256, 2021). "In colorectal cancer, low-glucose conditions trigger SLC2A3 expression through the AMPK/CREB1 pathway, promoting both glucose absorption and cell proliferation." (PMID 41268544, 2025). "Recently, GLUT3 has been reported to be significantly upregulated in colorectal cancer through AMP-activated protein Kinase (AMPK) and Cyclic AMP-Responsive Element-Binding protein 1 (CREB1) signaling." (PMID 38994998, 2024). "Overexpression of SIX1, another top-ranked CREB1-upregulated target, is an independent poor prognostic marker for stage I–III colorectal cancer." (PMID 34641874, 2021). "In colorectal cancer, UCA1 was found to function as an endogenous sponge by directly binding to miR-204-5p and promote the expression of a new target of miR-204-5p, CREB1." (PMID 28074092, 2016). "Interestingly, in colorectal cancer, AMPK-siRNA attenuated GLUT3 production by downregulating CREB1 phosphorylation." (PMID 38994998, 2024). "MiR-103b has been shown to target several molecules which play a role in carcinogenesis in other cell types, for example CCNE1, CDK2, CREB1, DICER, and PTEN, and colorectal cancer cell line studies indicate dysregulation of miR-103b expression can drive cancer progression." (PMID 29141625, 2017). "Moreover, research has demonstrated that cAMP responsive element binding protein 1 (CREB1) functions as a transcriptional activator of ZEB1, and that ZEB1, a pivotal regulator of EMT, significantly enhances the migratory capacity and EMT process in colorectal cancer cells." (PMID 40918458, 2025).
schizophrenia (48 papers, 2008 to 2026). A major psychotic disorder characterized by abnormalities in the perception or expression of reality. "The CREB binding protein is a co-activator of the CREB1 gene, which has been associated with response to treatment (in terms of cognitive improvement) in schizophrenia patients." (PMID 36980961, 2023). "Recent studies show that it may be important in regulating the development of neuronal progenitor cells, and physically interacts with other schizophrenia susceptibility genes, such as CREB1, AKT1 and ESR1." (PMID 35576194, 2022). "There is also some evidence of the association between CREB1 and schizophrenia." (PMID 30323833, 2018). "Several studies explored the role of CREB1 in psychiatric conditions, notably schizophrenia." (PMID 39518903, 2024). "Additionally, it has been well documented that a reduced CREB1 activity is highly connected with the pathophysiology of schizophrenia." (PMID 36744005, 2023). "Since it was previously reported that CRTC1 is expressed almost exclusively in the hypothalamus and CRTC3 is expressed in adipose tissue, the SIK1/CRTC2/CREB1 signaling pathway was selected and its involvement in the pathophysiology of schizophrenia was investigated in this study." (PMID 36744005, 2023). "In conclusion, this study suggests that altered SIK1/CRTC2/CREB1 and TWIST1/PI3K/Akt/GSK3β signaling pathways mediated by miR-25-3p is very likely to be associated with schizophrenia, revealing potential targets for the treatment and clinical diagnosis of schizophrenia." (PMID 36744005, 2023). "Antipsychotic treatment has also increased mRNA and protein levels of the gamma-aminobutyric acid A (GABAA) receptor and cAMP-responsive element-binding protein 1 (CREB1) in the rat nucleus accumbens, both of which are implicated in schizophrenia pathology and are regulated via PKA." (PMID 38248228, 2023). "Therefore, an in-depth study is required to further verify the involvement of the SIK1/CRTC2/CREB1 signaling pathway in schizophrenia." (PMID 36744005, 2023). "In addition, two possible downstream pathways of miR-25-3p, including the SIK1/CRTC2/CREB1 and TWIST1/PI3K/Akt/GSK3β signaling pathways, were examined with the schizophrenic rat model to explore their potential associations with schizophrenia." (PMID 36744005, 2023). "CREB1 is also a downstream substrate of the PKA pathway, and a relationship between CREB1 and the positive symptoms of schizophrenia has been proposed." (PMID 40562368, 2025). "It was suggested that synaptic genes, including CREB1, CREM, PPP3CB, and PRKAR1A, are involved in the etiology of schizophrenia-related psychiatric disorders and regulated by the cAMP/PKA/CREB signaling pathway." (PMID 30214393, 2018). "This study investigated whether miR-25-3p-mediated SIK1/CRTC2/CREB1 and TWIST1/PI3K/Akt/GSK3β signaling pathways are present in an animal model relevant to schizophrenia." (PMID 36744005, 2023). "In conclusion, the present study suggests that miR-25-3p-mediated SIK1/CRTC2/CREB1 and TWIST1/PI3K/Akt/GSK3β signaling pathways could be potential therapeutic targets for future antipsychotic drugs and candidate diagnosis biomarkers of schizophrenia." (PMID 36744005, 2023).
cognitive decline (46 papers, 2008 to 2025). "To summarize, the administration of NAT significantly lowered cognitive decline, neuroinflammatory pathways, and Tau protein and triggered the upregulation of CREB1 signaling, suggesting its neuroprotective role in AD-like conditions." (PMID 38091207, 2024). "CREB1 is a transcription factor involved in memory, cognition, and cognitive decline in aging." (PMID 30498565, 2018). "Therefore, hsa-miR-664a-3p was upregulated in AD patients, which downregulated CREB1 and BDNF expression levels, thereby leading to a cognitive decline in AD patients." (PMID 36040555, 2022).
liver cancer (42 papers, 2012 to 2026). An epithelial or non-epithelial malignant neoplasm that arises from the liver. "The CREB1/miR-922/ARID2 axis promoted liver cancer progression, with miR-922 targeting ARID2, while ARID2 overexpression counteracted malignancy." (PMID 40074445, 2025). "Overexpression of miR-122 acts by directly targeting CREB1 in gastric and liver cancers." (PMID 41318413, 2025). "The HULC may downregulate miR-372 and induce phosphorylation of cAMP responsive element binding protein 1 (CREB1) in liver cancer." (PMID 23843741, 2013). "Taken together, pifithrin-μ suppresses CREB1/CREBBP complex formation, CREB1-mediated transcription, and sorafenib resistance of mTOR-activated liver cancer cells." (PMID 39863613, 2025). "In our study, pifithrin-μ inhibited HSP70 to reduce the transcriptional activity of CREB1 and the expression of SESN3, consequently suppressing liver cancer cell proliferation and tumorigenesis." (PMID 39863613, 2025). "Here, CREB1 enhanced SESN3 expression by binding to SESN3 promoter and subsequently boosted the antioxidant capacity of liver cancer cells." (PMID 39863613, 2025). "Analysis of the array expression database revealed that CREB1 has a strong binding site in the upstream promoter region of MCU and MICU2 in liver cancer (HepG2) cells." (PMID 33114428, 2020). "Collectively, these observations suggest that miR-933 could enhance the expression of PKM2 via CREB1 and the interaction between PKM2 and CARM1 in human liver cancer." (PMID 38434754, 2024). "Even though SGC-CBP30 hinders the transcriptional activity of CREB1 and has the potential to alleviate sorafenib resistance in mTOR-activated liver cancer, SGC-CBP30 is metabolized too quickly in vivo and might not be suitable for clinical application." (PMID 39863613, 2025).
ischemia (41 papers, 2009 to 2025). A hypoperfusion of the BLOOD through an organ or tissue caused by a PATHOLOGIC CONSTRICTION or obstruction of its BLOOD VESSELS, or an absence of BLOOD CIRCULATION. "We have shown that increasing the expression of Creb1, enhances growth factor expression in peripheral nerves and accelerates vascular repair after ischemia." (PMID 31530804, 2019). "Foxo3a then translocates to the nucleus where it mediates suppression of Egr1/Creb1, the transcriptional regulators of multiple pro-angiogenic growth factors, mitigating recovery from ischemia." (PMID 31530804, 2019). "In order to determine the specific role of Creb1 in ischemia-induced blood flow recovery in vivo we over-expressed Creb1 in the hind limb using adenovirus." (PMID 31530804, 2019). "Thus, the data from this study indicates that neural Egr1 and Creb1 are important modulators of the vascular response to ischemia and mediate, in part, ischemic blood flow recovery in the hind limb." (PMID 31530804, 2019). "Therefore, in the absence of JNK3, Foxo3a is trapped in the cytoplasm and Egr1/Creb1 promote uninhibited transcription of multiple growth factors that enhance blood flow recovery from ischemia." (PMID 31530804, 2019). "Thus, JNK3 deficiency improves blood flow recovery by allowing full activity of Egr1/Creb1 to promote neuronal growth factor expression that contributes to the revascularization response to ischemia." (PMID 31530804, 2019).
pancreatic cancer (41 papers, 2010 to 2026). "Transcription of GDF15 is regulated by the cAMP response element binding protein 1 (CREB1) in a human pancreatic cancer cell line, making cAMP a likely second messenger also for exercise-induced GDF15 production in the liver." (PMID 36545337, 2022). "We next wondered whether Akt regulates the expression of factors responsible for pancreatic cancer cell migration through CREB1 phosphorylation." (PMID 30700740, 2019). "Kalli and colleagues studied pancreatic cancer and found that GDF-15 expression was upregulated in the metastatic process through the Akt/CREB1 pathway." (PMID 34070192, 2021). "Performing a phosphoprotein screening, we identified that solid stress activates the Akt/CREB1 pathway to transcriptionally regulate GDF15 expression, which eventually promotes pancreatic cancer cell migration." (PMID 30700740, 2019).
leukemia (40 papers, 2007 to 2025). A malignant (clonal) hematologic disorder, involving hematopoietic stem cells and characterized by the presence of primitive or atypical myeloid or lymphoid cells in the bone marrow and the blood. "cAMP Response Element Binding Protein (CREB1) is a TF known to be overexpressed in acute myeloid and leukemia cells." (PMID 31652275, 2019). "The dataset includes 20 samples (10 human leukemia cell lines K562 with CREB1 knocked-down and 10 K562 control cells) and 22.410 gene expression levels." (PMID 31652275, 2019). "Of note, CREB1 may enhance apoptosis, suggesting a mechanism for azacitidine’s anti-proliferative effects in CREB1-driven leukemias." (PMID 40728989, 2025). "Rothem et al26 have reported that reduced expression of transcription factors as CREB1, ATF1, USF1, FOS, JUN, Sp3, and Sp1 is responsible for a major decrease in RFC mRNA expression in the CCRF‐CEM and derived human leukemia cell lines." (PMID 32614991, 2020).
Parkinson disease (39 papers, 2013 to 2026). A progressive degenerative disorder of the central nervous system characterized by loss of dopamine producing neurons in the substantia nigra and the presence of Lewy bodies in the substantia nigra and locus coeruleus. "Besides being major contributors of neurodegeneration process, APP, CREB1, HSP90AA1, MAPT and PTEN have varying degree of interactions with many known Parkinson's disease genes (see CSPNW)." (PMID 24688734, 2013).
colon carcinoma (36 papers, 2009 to 2025). "In colon cancer, NE promotes cell proliferation and metastasis by activating the cAMP response element-binding protein-1–microRNA 373 (CREB1-miR-373) axis." (PMID 36499024, 2022). "In colon cancer cells, phosphorylation of CREB1 was induced by norepinephrine to facilitate cell proliferation, migration, and invasion." (PMID 35769513, 2022). "In colon cancer, miR-433 inhibits Creb1 and exerts an antitumor effect by inhibiting the cell cycle." (PMID 33494070, 2021). "We have demonstrated that NE promotes the progression of colon cancer via CREB1 activity‐dependent transcription, enhancing the expression of oncogenic miR‐373 and reducing the expression of the miR‐373 targets APC and TIMP2." (PMID 32118353, 2020). "NE promotes the progression of colon cancer via CREB1 activity‐dependent transcription, enhancing the expression of oncogenic miR‐373 and reducing the expression of the miR‐373 targets APC and TIMP2." (PMID 32118353, 2020). "Our data suggest that NE promotes colon cancer cell proliferation and metastasis by activating the CREB1–miR‐373 axis." (PMID 32118353, 2020). "Inhibition of CREB1 in NE‐treated cells decreased cell proliferation and invasion, and the presence of CREB1 was crucial in the NE‐induced progression of colon cancer." (PMID 32118353, 2020). "In this study, we demonstrated that CREB1 promotes miR‐373 expression by binding to its promoter in human colon cancer cells." (PMID 32118353, 2020). "We demonstrate that NE‐induced phosphorylation of cAMP response element‐binding protein 1 (CREB1) promotes proliferation, migration, and invasion of human colon cancer cells." (PMID 32118353, 2020). "Corvaisier and colleagues revealed that the phosphorylation of CREB1 was engaged in the chemoresistance and colon cancer relapse." (PMID 30523220, 2018). "Furthermore, NA has been shown to stimulate the proliferation and dissemination of colon cancer cells by inducing phosphorylation of cAMP response element-binding protein 1 (CREB1), thereby activating the CREB1/miRNA-373 axis." (PMID 37610689, 2024). "Therefore, CREB1 binds to the promoter of miR‐373 and activates the transcription of miR‐373 in colon cancer cells." (PMID 32118353, 2020). "In this study, we used human colon cancer cells to show that NE activates CREB1." (PMID 32118353, 2020). "In colon cancer cell lines, silencing of stanniocalcin 1 (STC1) reverses the tumor-promoting effects of miR-101 down-regulation, and overexpression of miR-101 generates anti-tumor effects by targeting the cAMP-responsive element binding protein 1 (CREB1) and Notch signaling pathway." (PMID 36497343, 2022).
Insulin resistance (35 papers, 2010 to 2025). Increased resistance towards insulin, that is, diminished effectiveness of insulin in reducing blood glucose levels. "Moreover, Creb1 has been shown to aggravate insulin resistance by stimulating the expression of the bZiP factor ATF3 which represses Pparγ expression and inhibits adipocyte differentiation." (PMID 33912553, 2021).
glioblastoma (34 papers, 2012 to 2025). The most malignant astrocytic tumor (WHO grade IV). "However, there is still evidence that CREB1 inhibits the proliferative effects of the stress-induced acetylcholinesterase variant AChE-R in glioblastoma, suggesting a controversial or tissue-specific role for CREB1 in human cancers." (PMID 33921660, 2021). "Inhibition of CREB1 has displayed reduced tumor growth and invasion in preclinical glioblastoma models." (PMID 39606019, 2024). "Some evidences showed that CREB1 inhibited cell proliferation in glioblastoma." (PMID 27801665, 2016). "However, there is still evidence showing that CREB1 suppresses the glioblastoma proliferative effect of the stress-induced acetylcholinesterase variant AChE-R, suggesting a controversial or tissue-specific role of CREB1 in human cancers." (PMID 25825983, 2015). "Furthermore, single-cell RNA sequencing (scRNA-seq) has provided crucial insights into the transcriptomic heterogeneity of glioblastomas, identifying key genes such as PDGFA, PDGFRA, CREB1, and PLAT that are strongly linked to tumor progression and patient survival." (PMID 40332008, 2025). "Our bioinformatics studies by Targetscan 7.1 and miRwalk 2.0 site have predicted that miR-548x and miR-4698 could simultaneously target 3ʹUTR of PI3KCB, PI3KCA, PDK1, AKT1, mTOR, MDM2, Rheb, and CREB1 genes that some of them were upregulated in glioblastoma sample according TCGA deta." (PMID 32005873, 2020). "According to our bioinformatics studies in the TargetScan 7.1 and miRwalk 2.0 database, we predicted that some miRNAs, as well as miR-548x and miR-4698 could target some genes that are overactive in the PI3K/AKT pathway (PI3KCB, PI3KCA, PDK1, AKT1, Rheb, MDM2, mTOR, and CREB1) in glioblastoma." (PMID 32005873, 2020). "Since in patient-derived in vivo models of glioblastoma, CREB1 levels have been found to determine the expression of TGFB2, CREB1 has been proposed a biomarker to stratify GBM patients for anti-TGF-β treatments and eventually as a therapeutic target in anti-TGF-β therapies." (PMID 33478130, 2021).
Huntington disease (33 papers, 2010 to 2025). Huntington disease (HD) is a rare neurodegenerative disorder of the central nervous system characterized by unwanted choreatic movements, behavioral and psychiatric disturbances and dementia. "In the enriched signaling pathways (p-value <0.10), we identified genes such as mitochondrial-encoded NADH dehydrogenase 5 (ND5 MTND5) and mitochondrial-encoded NADH dehydrogenase 6 (ND6 MTND6) that are present in the “CREB1-dependent transcriptional deregulation pathway in Huntington’s disease”." (PMID 36816031, 2023). "Interruption of CREB1 activity in mitochondria leads to decreased expression of mitochondrial-encoded MTND6 and MTND5, downregulating complex I-dependent mitochondrial respiration and consequent mitochondrial dysfunction and neuronal cell death in Huntington’s disease." (PMID 36816031, 2023).